ATG7 (autophagy related 7)
Diseases named in the same sentence as ATG7 in open-access papers (continued):
Sharing a sentence is not in itself a finding about the gene and the disease.
asthma (12 papers, 2012 to 2025). "Furthermore, genetic polymorphisms in Atg5 and Atg7 genes were linked to airway remodeling and impairment in respiratory system mechanics in individuals with pediatric and adult asthma." (PMID 37627282, 2023). "We hypothesized that ATG5 and ATG7 polymorphisms and/or dysregulated expression of these genes are associated with childhood asthma." (PMID 22536318, 2012). "miR-192-5p has been reported to inhibit autophagy by separately targeting matrix metalloproteinase (MMP) 16 and autophagy-related 7 (ATG7), which allow airway remodeling and exert antifibrotic effects, thereby relieving asthma." (PMID 35572723, 2022). "Associations between two genes in the autophagy pathway, ATG5 and ATG7, with childhood asthma were investigated." (PMID 22536318, 2012). "By screening the autophagy genes ATG5 and ATG7, we found evidence of association with variants in ATG5 with childhood asthma." (PMID 22536318, 2012). "Human polymorphisms in Atg5 and Atg7 are not linked to susceptibility to or severity of asthma, but they are linked with neutrophilic inflammation in the sputum of asthmatic patients, suggesting a link to non-Th2 asthma." (PMID 37627282, 2023). "Furthermore, the expression of ferritinophagy-related proteins (NCOA4, ATG-5, and ATG-7) in the lung tissues was elevated upon the occurrence of asthma but was then repressed after the treatment of Ferr-1 and 3-MA." (PMID 35154576, 2022). "Polymorphisms of Atg5 and Atg7 are not linked to asthma susceptibility or severity, but are associated with neutrophilic inflammation in sputum, suggesting a link to non-T2 asthma." (PMID 35608088, 2022). "In a study about asthma, miR-192-5p is reported to attenuate autophagy in asthma by targeting autophagy-related 7 (ATG7), overexpression of miR-192-5p is suggested to down-regulate ATG7 levels." (PMID 32406504, 2020). "Using genetic and experimental approaches, we examined the association of 13 HapMap-derived tagging SNPs in ATG5 and ATG7 with childhood asthma in 312 asthmatic and 246 non-allergic control children." (PMID 22536318, 2012). "Among asthma cases, we next examined whether ATG5 or ATG7 SNPs were associated with pulmonary function tests, including FEV1 (% predicted) and FEV1/FVC (% predicted)." (PMID 22536318, 2012). "The typical differential genes concentrated in autophagy-related signaling pathways in MC4 (e.g., BECN1, ATG7 and LRRK2) were found to be downregulated in the asthma group compared with the control group (p < 0.05)." (PMID 36439114, 2022). "Its overexpression was associated with decreased levels of ovalbumin-specific IgE, IL-4, IL-5, and IL-13, contributing to improved asthma outcomes by limiting airway remodeling and autophagy through the downregulation of matrix metalloproteinase (MMP)-16 and autophagy related 7 (ATG7)." (PMID 40871238, 2025). "Our data support a role for the autophagy pathway, and specifically ATG5 but not ATG7, in childhood asthma." (PMID 22536318, 2012). "Moreover, Lou and coworkers demonstrated that the levels of miR-192-5p are decreased in asthmatic mice, and the overexpression of miR-192-5p alleviates airway remodeling and autophagy in asthma by targeting matrix metalloproteinase-16 (MMP-16) and autophagy-related 7 (ATG7) in vitro and in vivo." (PMID 33708127, 2021).
Huntington disease (12 papers, 2008 to 2025). Huntington disease (HD) is a rare neurodegenerative disorder of the central nervous system characterized by unwanted choreatic movements, behavioral and psychiatric disturbances and dementia. "Previous studies have shown that the polymorphism (V471A) in ATG7 gene that substitutes alanine for valine has been significantly associated with an earlier onset of Huntington's disease (HD)." (PMID 30407747, 2018). "More specifically, the V471A polymorphism in ATG7 correlates with an earlier disease onset of 4 years in a mixed group of Huntington disease populations." (PMID 26404030, 2015). "And in humans, a polymorphism study of more than 900 European Huntington’s disease patients revealed that one variant of Atg7 (Atg7V471A) is statistically correlated with early onset of Huntington’s disease." (PMID 22621211, 2012). "In line with an important role of autophagy in prevention of protein aggregation, several mutations in human ATG7 have been linked to neurodegenerative disease, including a V471A polymorphism in ATG7 that correlates with an earlier disease onset in Huntington disease populations." (PMID 31450711, 2019). "Although the relationship between ATG7 and schizophrenia has yet to be studied, Genecards shows that this gene is significantly associated with neuronal abnormalities and mental illness, i.e., Neurodegeneration Caused by Brain Iron Accumulation, Huntington’s Disease, and Other Conditions." (PMID 36993785, 2023). "Recently, we identified the V471A polymorphism in the autophagy-related gene ATG7, a key component of the autophagy pathway that plays an important role in HD pathogenesis, to be associated with the age at onset in a large group of European Huntington disease patients." (PMID 23894380, 2013). "The ATG7 polymorphisms in the coding region seem to be associated with Huntington’s disease, while other studies about evaluated polymorphisms in ATG7 are in the same way about not association of this polymorphism with PD." (PMID 40093192, 2025).
cardiac hypertrophy (10 papers, 2013 to 2024). "In addition, cardiomyocyte-specific deletion of Atg5 caused cardiac hypertrophy and dysfunction, and cardiomyocyte-specific deletion of Atg7 caused cardiac systolic dysfunction and reduced the survival of mice." (PMID 37733896, 2024). "Cardiac-specific Atg5 or Atg7 deficiency leads to cardiac hypertrophy." (PMID 23737997, 2013). "Although no studies have yet explored the consequences of disrupted cardiac ATG7 expression, familial ATG5 mutations are associated with severe cardiac hypertrophy leading to dilated cardiomyopathy by 10 months." (PMID 36939901, 2023). "The cardiomyocyte-specific knockout of Atg7 aggravates the MI/R injury with cardiac hypertrophy, contractile dysfunction, myofibrillar disarray and severe cardiac fibrosis, most probably due to CLP36 accumulation in cardiomyocytes." (PMID 27512143, 2016). "Mice with cardiac-specific autophagy related 5 (ATG5) or autophagy related 7 (ATG7) ablation, required for optimal autophagic responses, develop cardiac hypertrophy, left ventricular dilation, contractile dysfunction and premature death, along with mitochondrial misalignment and aggregation." (PMID 39456761, 2024). "Here, we find that the knockout of Atg7 in cardiomyocytes aggravates the injury with cardiac hypertrophy, contractile dysfunction, myofibrillar disarray and severe cardiac fibrosis, which also indicate that autophagy is essential for protecting cardiomyocytes from MI/R injury." (PMID 27512143, 2016). "After ischaemia-reperfusion treatment, the Atg7-deficient mice showed aggravated MI/R injury with cardiac hypertrophy, contractile dysfunction, myofibrillar disarray and severe cardiac fibrosis, and CLP36 was found to be accumulated in ischaemia-reperfusion treated Atg7-deficient cardiomyocytes." (PMID 27512143, 2016). "Thus, cardiomyocyte-specific disruption of ATG7 aggravated the MI/R injury with cardiac hypertrophy, contractile dysfunction, myofibrillar disarray and severe cardiac fibrosis." (PMID 27512143, 2016). "However, in Atg7+/+ SM22α-Cre+ mice AngII treatment caused hypertension without concomitant cardiac hypertrophy, whereas in Atg7F/F SM22α-Cre+ mice cardiac hypertrophy and fibrosis was present without the occurrence of hypertension." (PMID 33071811, 2020). "The expression levels of autophagy-related proteins (ATG7 and LC3A/B) were significantly reduced in aged WT and Y-Sesn2 KO hearts during cardiac hypertrophy, while levels of apoptosis-related proteins (BCL2 and BAX) increased." (PMID 32863202, 2020).
cervical cancer (9 papers, 2013 to 2024). A primary or metastatic malignant neoplasm involving the cervix. "ARCSP induced high expression of p-AMPK, p-raptor, LC3B-II, atg7, and p62 and low expression of p-mTOR and p-p70s6k in cervical cancer cells." (PMID 32962728, 2020). "ATG7 knockdown inhibits the artesunate-induced autophagy of cervical cancer cells, suggesting that artesunate may upregulate the ferroptosis-inducing ATG7 gene." (PMID 38892270, 2024). "Besides other targets, siRNA mediated knockdown of PPAN resulted in upregulation of the autophagy factor ATG7 in HeLa cervical cancer cells when using the functional PPAN si RNA, termed si PPAN-B as previously." (PMID 34944838, 2021). "Furthermore, miR-20a expression has been related to the malignant process of cervical cancer, especially invasion and metastasis by targeting ATG7 and TIMP2." (PMID 27916938, 2016). "Our results suggest that miR-20a expression may be related with malignant process of cervical cancer, especially invasion and metastasis by targeting ATG7 and TIMP2." (PMID 25803820, 2015). "Taken together, NJXA-promoted proliferation inhibition and mitophagy induction were both attenuated by ATG7 knockdown, illustrating that mitophagy is at least partially responsible for the anticancer effect of NJXA on cervical cancer cells." (PMID 34065886, 2021). "RAME treatment increased the mRNA levels of ATG genes (ULK1, ATG5, BECN1, ATG7, ATG12, and ATG13) dose dependently in cervical cancer cells." (PMID 31387554, 2019).
Hyperglycemia (9 papers, 2015 to 2023). An increased concentration of glucose in the blood. "Deletion of Atg7 has been shown to cause profound destruction of endocrine pancreatic tissue and fatal hyperglycaemia." (PMID 35372352, 2022). "Inhibition of Atg7 in islet cells has been demonstrated to cause fatal hyperglycaemia." (PMID 35372352, 2022). "Deficient autophagy in mice resulting from the knockout of the autophagy-related gene Atg7 leads to impaired glucose tolerance, reduced insulin levels, decreased pancreatic β-cell count, and hyperglycemia." (PMID 37894898, 2023). "Autophagy induction by adenoviral-mediated ATG7-overexpression maintains a cardioprotective, anti-inflammatory and pro-angiogenic paracrine profile of CSCs exposed to hyperglycemia for 1 week." (PMID 35365624, 2022). "Human umbilical vein endothelial cells (HUVECs) were exposed to conditioned media from ad-ATG7-transduced CSCs in hyperglycemia, and they were able to form significantly more closed loops with a significantly higher total tube length, as compared to ad-LacZ-transduced CSCs." (PMID 35365624, 2022). "Finally, autophagy induction by ATG7-overexpression during hyperglycemia can significantly preserve cell viability in CSCs, which were subsequently exposed to nutrient deprivation, reducing hyperglycemia-induced impairment of cell resistance to stress." (PMID 35365624, 2022). "In order to test whether autophagy reactivation could oppose the depletion of Sca1+ cells during high glucose stress, CSCs were transduced with Ad-ATG7 at day 4 of hyperglycemia treatment." (PMID 35365624, 2022). "When bred to ob/+ mice to induce metabolic stress, mice with myeloid cell-specific deletion of autophagy-related 7 (ATG7) displayed increased CLS numbers, activated NLRP3 inflammasome and IL-1β production in adipose tissue, as well as hyperglycemia." (PMID 37153549, 2023). "Our results showed that autophagy was significantly activated in response to hyperglycemia, and enforced expression of H19 in diabetic rats decreased the number of autophagosomes and reduced the expression of LC3-II, BECN1 and ATG7." (PMID 27903964, 2017). "LC3II/LC3I ratio was significantly decreased due to acute hyperglycemia, however, other autophagy-related proteins such as Beclin-1, total and Triton X-100-insoluble SQSTM1/p62, phospho-ULK1 (Ser555), ATG7 and BNIP3 were unchanged in AHG group." (PMID 26581389, 2015). "In spite of a decreased LC3II/LC3I ratio, other markers of autophagy, such as ATG7, ULK1 phopsphorylation, Beclin 1 and SQSTM1/p62, were not modulated by acute hyperglycemia." (PMID 26581389, 2015).
neuroblastoma (9 papers, 2014 to 2023). Neuroblastoma (NB) is the most common solid, extracranial childhood tumor. "Others have reported that depletion of TDP-43 reduces the mRNA level of Atg7, by destabilizing Atg7 mRNA, which causes an impairment in autophagy and the accumulation of polyubiquitinated proteins and p62 in neuroblastoma cells." (PMID 29282133, 2017). "It has been shown that downregulation of ATG7 can compensate the loss of mitochondria in PTEN-induced kinase 1 (PINK1) deficient dopaminergic human neuroblastoma cells, likely supporting the potential role of ATG7 in PINK1 mutation-related familial Parkinson’s disease." (PMID 26404030, 2015). "The study found that miR-20a-5p inhibited neuroblastoma proliferation and autophagy and promoted cell apoptosis through negative regulation of ATG7." (PMID 34249133, 2021). "It has previously been stated that the natural compound 18α-glycyrrhetinic acid and OxyR-mediated autophagy display accumulation of Atg5, Atg7, and Beclin-1 in neuroblastoma cells." (PMID 33800526, 2021). "For that purpose we generated a stable ATG7 overexpressing B35 neuroblastoma cells." (PMID 37749555, 2023). "A recent proteomic study revealed that upregulation of ATG7 was accompanied by the upregulation of ferritinophagy-related proteins, such as LC3, ferritin (FTL, FTH1), and NCOA4 in an arsenic trioxide-treated neuroblastoma cell line." (PMID 37522124, 2023). "In this study, CK-induced early-stage autophagy in neuroblastoma cells was evidenced by an increased number of autophagosomes and increased expression of the autophagy markers LC3-II, Atg7, and BECN proteins." (PMID 31480534, 2019). "The expression of LC3B and ATG3, ATG5, ATG7, ATG12 proteins was also markedly up-regulated after BIX01294 treatment in neuroblastoma cells." (PMID 27934912, 2016). "Atg4B, Atg7 and Atg9B were not detectable in CSF; however, the antibodies used detected these proteins in human SH-SY5Y neuroblastoma cell lysates (data not shown)." (PMID 24101586, 2014).
osteosarcoma (9 papers, 2013 to 2025). A usually aggressive malignant bone-forming mesenchymal neoplasm, predominantly affecting adolescents and young adults. "Low expression of ATG7 is likely a common genetic variant in all patients with osteosarcoma metastases." (PMID 40276062, 2025). "ATG7 expression is associated with the regulation of oxidative stress in osteosarcoma." (PMID 38586328, 2024). "This indicates that ATG7 plays a crucial role in osteosarcoma autophagy, underscoring its importance for further research." (PMID 40276062, 2025). "More importantly, ATG7 plays a significant role in osteosarcoma autophagy, providing new clues for exploring immunotherapeutic approaches for osteosarcoma patients." (PMID 40276062, 2025). "To assess the potential of ATG7 as a biomarker and therapeutic target for osteosarcoma metastases, we analyzed the expression of ATG7 in tissue microarrays using immunohistochemistry." (PMID 40276062, 2025). "Silenced the ATG7 gene can boost osteosarcoma cell proliferation and migration while inhibiting oxidative stress and iron death." (PMID 38586328, 2024). "Our results indicate that honokiol-induced autophagy in osteosarcoma cells is dependent on the upregulation of Atg7." (PMID 29410403, 2018). "We have examined the effect of 2-ME on autophagosome formation in osteosarcoma cells that have been depleted with ATG7 expression after transfection with siRNAs directed against ATG7 gene." (PMID 23527187, 2013). "Although the complex link between ATG7 and osteosarcoma remains puzzling, alterations in autophagy are increasingly associated with tumors, and targeting and regulating ATG7 may constitute a promising therapeutic approach." (PMID 40276062, 2025). "Moreover, the production of intracellular ROS, activation of the MAP kinase ERK, and upregulation of Atg7 were essential to the induction of honokiol-induced autophagy in osteosarcoma cells." (PMID 29410403, 2018). "In addition, 2-ME-dependent autophagosome formation in osteosarcoma cells requires ATG7 expression." (PMID 23527187, 2013). "First, we identified MAPK1, CFH, ATG7, and DDIT4 as independent prognostic factors in osteosarcoma patients via Cox regression analysis." (PMID 40276062, 2025). "In this study, it was demonstrated that ebastine promoted autophagy by upregulating the protein expression of ATG7, ATG16 and LC3B in osteosarcoma cells." (PMID 36632464, 2023). "The activation of Atg5/Atg7-dependent pathways through the upregulation of LC3B-II, Atg5, and Atg7 levels was observed in honokiol-treated osteosarcoma HOS and U2OS cells and leads to the accumulation of autophagic vacuoles." (PMID 31877856, 2019). "However, the silencing of Atg7 with siRNA reduced HNK-induced LC3B-II protein levels, indicating that Atg7 is involved in HNK-induced autophagy in osteosarcoma cells." (PMID 29410403, 2018). "The data also demonstrate that osteosarcoma cells transfected with siRNAs for ATG7, do not respond to 2-ME-mediated autophagosome induction, suggesting that 2-ME-mediated effects require ATG7 protein expression." (PMID 23527187, 2013). "2-ME treatment does not induce autophagasome formation in osteosarcoma cells transfected with ATG7 siRNAs but induces autophagasome in control cells that have been transfected with non-specific siRNAs." (PMID 23527187, 2013).
thyroid cancer (9 papers, 2014 to 2025). "To investigate the impact of LINC00162 knockdown and sorafenib treatment on autophagy in thyroid cancer cells, we analyzed the expression levels of ATG5, ATG7, and MAP1LC3B genes in B-CPAP cancer cells." (PMID 40804316, 2025). "To better understand the role of LINC00162 in thyroid cancer progression, we evaluated the expression of the autophagy-related genes ATG5, ATG7, and MAP1LC3B." (PMID 40804316, 2025). "Taken together, these data show that the inhibitory effects of Obatoclax on the late steps of autophagy are independent of those on cell survival, and suggest that Atg7 might have autophagy-independent functions that are necessary for the ability of Obatoclax to kill thyroid cancer cells." (PMID 27144341, 2016).